TRIM59 (tripartite motif containing 59)
Diseases named in the same sentence as TRIM59 in open-access papers (continued):
Sharing a sentence is not in itself a finding about the gene and the disease.
neuroblastoma (6 papers, 2019 to 2025). Neuroblastoma (NB) is the most common solid, extracranial childhood tumor. "Based on the mechanism of IRF6 regulation by TRIM59-mediated ubiquitination, we assessed the functional phenotype of neuroblastoma cells after altering the expression levels of TRIM59 and IRF6." (PMID 40796729, 2025). "Kaplan‒Meier analysis showed that neuroblastoma patients with high TRIM59 expression had worse overall and event-free survival compared to those with low TRIM59 expression." (PMID 40796729, 2025). "TRIM59 was found to be upregulated and positively correlated with β-catenin in neuroblastoma tissues, and knocking down TRIM59 inhibited cell proliferation by suppressing the Wnt/β-catenin signaling pathway." (PMID 36249749, 2022). "To explore the function of TRIM59 in neuroblastoma, we first measured expression of TRIM59 in four neuroblastoma cell lines, SH-SY5Y, SK-N-SH, SK-N-BE2, and NB-1." (PMID 30389710, 2019). "TRIM59 was highly overexpressed in neuroblastoma tissues compared with normal tissues due to TRIM59 regulating cell proliferation and apoptosis through Wnt/β-catenin signaling." (PMID 30389710, 2019). "In conclusion, TRIM59 was up-regulated in neuroblastoma, and TRIM59 knockdown inhibited cell proliferation by down-regulating the Wnt/β-catenin signaling pathway in neuroblastoma." (PMID 30389710, 2019). "Our results demonstrated that both mRNA and protein levels of TRIM59 were overexpressed in human neuroblastoma tissues." (PMID 30389710, 2019). "Given that TRIM59 knockdown induced apoptosis, we examined expression of apoptosis-related proteins in neuroblastoma cells." (PMID 30389710, 2019). "In the present study, real-time PCR and Western blot were used to measure mRNA and protein levels of TRIM59 in four neuroblastoma cell lines and in neuroblastoma tissues." (PMID 30389710, 2019). "Given that TRIM59 knockdown inhibited cell proliferation, we next measured expression levels of TRIM59 in human neuroblastoma tissues." (PMID 30389710, 2019). "In summary, we demonstrated that knockdown TRIM59 inhibits cell proliferation and induces apoptosis in neuroblastoma cells." (PMID 30389710, 2019). "Moreover, IRF6 expression was downregulated due to an increased level of ubiquitination mediated by the E3 ligase TRIM59, which correlated with unfavorable outcomes in neuroblastoma patients." (PMID 40796729, 2025). "In addition, Pearson correlation analysis demonstrated a positive correlation between TRIM59 and β-catenin in neuroblastoma tissues (r = 0.7771)." (PMID 30389710, 2019). "In addition, β-catenin was up-regulated and was positively correlated with TRIM59 in neuroblastoma tissues." (PMID 30389710, 2019). "In addition, TRIM59 was up-regulated and positively related with β-catenin in neuroblastoma tissues." (PMID 30389710, 2019). "In the present study, we identified the function of TRIM59 in neuroblastoma for the first time, suggesting that TRIM59 may act as oncogene via the regulation of Wnt/β-catenin signaling." (PMID 30389710, 2019). "In contrast, TRIM59 overexpression promoted cell proliferation in SK-N-BE2 cells, suggesting that TRIM59 may play an oncogenic role in neuroblastoma." (PMID 30389710, 2019). "In the present study, we first assessed the function of TRIM59 in neuroblastoma." (PMID 30389710, 2019). "Additionally, IRF6 expression was diminished in neuroblastoma due to E3 ligase TRIM59-mediated polyubiquitination, and may reverse the promoting effect of TRIM59 overexpression on cell proliferation and glycolysis." (PMID 40796729, 2025). "However, the exact role of TRIM59 in neuroblastoma still needs to be delineated." (PMID 30389710, 2019). "However, the exact role of TRIM59 in neuroblastoma is unknown." (PMID 30389710, 2019). "Our data showed that TRIM59 knockdown inhibits cell proliferation while inducing apoptosis in SH-SY5Y and SK-N-SH neuroblastoma cell lines." (PMID 30389710, 2019).
Sepsis (6 papers, 2020 to 2024). Sepsis is defined as life-threatening organ dysfunction caused by a dysregulated host response to infection. "Mechanistically, METTL3 inhibited endothelial injury in sepsis-induced ARDS through Trim59-associated NF-κB inactivation." (PMID 35693774, 2022). "Mechanistically, METTL3 inhibits endothelial injury in sepsis-induced ARDS through Trim59-associated NF-κB inactivation." (PMID 35693774, 2022). "To confirm the effect of TRIM59 deficiency on immune cells in mice with sepsis, we collected the peripheral blood, spleen, and mesenteric lymph node (mLN) from sham or CLP group mice 24 h after surgery." (PMID 32133014, 2020). "In summary, the loss of TRIM59 exacerbated both the local and systemic inflammatory response in sepsis, and TRIM59 also played an anti-inflammatory role in resting state." (PMID 32133014, 2020). "All results indicated that the loss of TRIM59 aggravated the host's response to sepsis." (PMID 32133014, 2020). "N6-methyladenosine modification of Trim59 mRNA, mediated by METTL3, is implicated in the prevention of acute respiratory distress syndrome induced by sepsis." (PMID 38993561, 2024). "In conclusion, we proved that TRIM59 in myeloid derived macrophages protected mice from sepsis by regulating inflammation and phagocytosis." (PMID 32133014, 2020). "We also found that bacteria loads were increased in Trim59-cKO mice with sepsis, and phagocytosis and Fcγ receptors were reduced in BMDMs from Trim59-cKO mice." (PMID 32133014, 2020). "We found a large number of neutrophils infiltrated the peripheral blood of Trim59-cKO mice with sepsis, which indicates a more severe inflammatory response." (PMID 32133014, 2020). "In our study, TRIM59 conditional knockout mice were bred to explore the effect of TRIM59 in myeloid derived macrophages in sepsis." (PMID 32133014, 2020). "Our further analysis indicated that Fcγ receptors were up-regulated by TRIM59, which confirmed the role of TRIM59 in macrophage phagocytosis in sepsis." (PMID 32133014, 2020). "The results of our study indicated that TRIM59 protected mice from sepsis by regulating inflammation and phagocytosis in macrophages." (PMID 32133014, 2020). "Our study demonstrated for the first time that TRIM59 protects mice from sepsis by regulating inflammation and phagocytosis in macrophages." (PMID 32133014, 2020). "It was reported that TRIM59 knockout aggravated the pulmonary injury induced by sepsis." (PMID 37978515, 2023). "TRIM59 in myeloid-derived macrophages protected mice from sepsis by regulating inflammation and phagocytosis and could directly regulate inflammation via the NF-κB signaling pathway, but the specific binding site or molecules involved remain unknown." (PMID 35693774, 2022). "Previous studies have demonstrated that tripartite motif 59 (TRIM59) was involved in NF-κB signaling and could promote phagocytosis of macrophages, but the role of TRIM59 in sepsis is still unknown." (PMID 32133014, 2020). "Therefore, we concluded that TRIM59 protected mice from sepsis by regulating inflammation and phagocytosis in macrophages." (PMID 32133014, 2020). "We hypothesized that TRIM59 would regulate secretion of cytokines by activating the NF-κB signaling pathway, which could aggravate sepsis." (PMID 32133014, 2020). "Phagocytosis plays an important role in bacteria invasion, so we hypothesized that TRIM59 could affect sepsis by regulating macrophage phagocytosis." (PMID 32133014, 2020). "Moreover, TRIM59 deficiency in macrophages did not affect DSS-induced colitis or LPS-induced sepsis in mice." (PMID 38992114, 2024). "However, the role of TRIM59 in sepsis has not been explored." (PMID 32133014, 2020).
cholangiocarcinoma (4 papers, 2019 to 2021). A carcinoma that arises from the intrahepatic biliary tree (intrahepatic cholangiocarcinoma) or from the junction, or adjacent to the junction, of the right and left hepatic ducts (hilar cholangiocarcinoma). "For instance, the high expression of TRIM59 in cholangiocarcinoma cells could regulate cell proliferation via the phosphatidylinositol-3-kinase (PI3K)/AKT/mammalian target of rapamycin (mTOR) signaling pathway." (PMID 33791238, 2021).
Graves disease (4 papers, 2018 to 2023). Graves' disease is an autoimmune disorder that leads to overactivity of the thyroid gland (hyperthyroidism).It is caused by an abnormal immune system response that causes the thyroid gland to produce too much thyroid hormones. "While altered DNA methylation leading to decreased prediction accuracy was found for both TRIM59 and FHL2 in the group of Graves’ disease, indicating differences in how various diseases affect the methylation of age-correlated CpGs." (PMID 37621446, 2023).
melanoma (4 papers, 2019 to 2024). A malignant, usually aggressive tumor composed of atypical, neoplastic melanocytes. "Previous study suggested that TRIM59 loss in M2 macrophages promotes melanoma migration and invasion by upregulating MMP-9 and Madcam1." (PMID 32867817, 2020). "In conclusion, our study suggested that expression of TRIM59 in macrophages potentially restricts melanoma progression and metastasis, and its loss has pro-tumoral effects via induction of TNF-α." (PMID 31600735, 2019). "In the present work, TRIM59 deficiency stimulated the metastatic potential of melanoma cells, suggesting that expression of TRIM59 in macrophages may have antitumor effects." (PMID 31600735, 2019). "To investigate whether deletion of TRIM59 in macrophages affects the metastatic potential of melanoma cells, we polarized control and TRIM59-deficient bone marrow-derived macrophages to the M2 phenotype and collected the respective conditioned media (CM)." (PMID 31600735, 2019). "In preliminary experiments, we also observed that the supernatant of RAW264.7 cells overexpressing TRIM59 had a strong cytotoxic effect on mouse B16 melanoma cell lines, and this effect was attenuated by a TRIM59-blockingantibody (data not shown)." (PMID 31600735, 2019). "Transcriptome analysis revealed significant upregulation of MMP-9 and Madcam1 in melanoma cells exposed to TRIM59-/--M2 CM." (PMID 31600735, 2019). "In this study, we generated conditional KO mice with myeloid-specific deletion of TRIM59 (TRIM59-CKO mice) and evaluated the effects of TRIM59-/--M2 macrophages on the metastatic behavior of melanoma B16-F0 and B16-F10 cells." (PMID 31600735, 2019). "To investigate the mechanism by which TRIM59-/--M2 macrophage CM promoted the migration and invasion of melanoma cells, we used ELISA to detect the concentrations of relevant cytokines in M2 macrophage supernatants." (PMID 31600735, 2019). "Additional assays were conducted in human melanoma A375 cells pre-treated with CM from M2-polarized TRIM59+/+ and TRIM59-/- human THP1 macrophages." (PMID 31600735, 2019). "Next, melanoma B16-F0 and B16-F10 cells were incubated with CM from WT-M2 or TRIM59-/--M2 macrophages." (PMID 31600735, 2019). "To determine whether TRIM59 expression in macrophages influences melanoma growth and migration/invasion, we subcutaneously injected B16-F10 mouse melanoma cells into WT and myeloid-specific TRIM59-CKO mice." (PMID 31600735, 2019). "Exposure to TRIM59-/--M2 macrophage supernatant promoted migration and invasion of B16 melanoma cells, and inhibitory experiments indicated that overexpression of TNF-α by TRIM59-deficient M2 macrophages and activation of ERK, and perhaps PI3K, signaling in B16 melanoma cells mediated these effects." (PMID 31600735, 2019). "In addition, subcutaneous tumor growth and formation of lung metastases of melanoma cells were evaluated in TRIM59-CKO animals." (PMID 31600735, 2019). "This study shows that the growth of B16 melanoma allografts was stimulated by myeloid-specific TRIM59 knockdown in host mice, indicating that TRIM59 expression in TAMs may prevent or attenuate melanoma progression." (PMID 31600735, 2019). "The culture supernatant from macrophages overexpressing TRIM59 has a cytotoxic effect on melanoma, but the mechanism remains unclear." (PMID 31600735, 2019). "This evidence highlights that upregulation of TRIM59 in TAMs could be an effective way to attenuate or prevent tumor growth, in melanoma and perhaps other cancers." (PMID 31600735, 2019). "Independent knockdown of either MMP-9 or Madcam1 by shRNA in melanoma cells inhibited EMT and invasion induced by TRIM59-/--M2 macrophage CM, and attenuated the growth of subcutaneous B16-F10 tumors and reduced lung metastasis burden in TRIM59-CKO-mice." (PMID 31600735, 2019).
melanoma (continued). "The direct interaction between TRIM59 and PIAS1 significantly enhances PIAS1-STAT1 interaction, thereby suppressing the JAK2-STAT1 signaling pathway and nitric oxide (NO) production in macrophages, which subsequently promotes melanoma growth." (PMID 39451518, 2024). "In our study, TRIM59-/ -macrophages mediated upregulation of the PI3K and ERK signaling pathways in B16 melanoma cells, promoting MMP-9 and Madcam1 expression and stimulating migration and invasion in vitro, as well as tumorigenesis, EMT, and metastasis in an in vivo tumor model." (PMID 31600735, 2019).
endometriosis (3 papers, 2022 to 2025). The growth of functional endometrial tissue in anatomic sites outside the uterine body. "Likewise, TRIM59 acts as a booster of proliferation and invasion of endometriosis-associated cancer, such as ovarian, breast, and cervical cancers." (PMID 36262826, 2022). "However, overexpression of TRIM59 is also observed in endometriosis, with TRIM59 promoting the invasion of ectopic endometrial stromal cells." (PMID 40558830, 2025). "Notably, TRIM59 in ectopic lesions, through ubiquitination, regulates PPM1A degradation, activating the TGF-β/SMAD2/3 pathway and thus promoting fibrosis in endometriosis." (PMID 38735939, 2024).
glioblastoma (3 papers, 2019 to 2021). The most malignant astrocytic tumor (WHO grade IV). "Another group demonstrated that nuclear TRIM59, as an E3 ligase, led to the ubiquitination of mH2A1 and affected mH2A1 stability in glioblastoma." (PMID 34106407, 2021). "A study in glioblastoma (GBM) cells suggests that TRIM59 promotes GBM tumorigenesis through interaction with nuclear STAT3 and maintains its transcriptional activation by preventing its dephosphorylation." (PMID 31820796, 2019).
glioma (3 papers, 2019 to 2023). A benign or malignant brain and spinal cord tumor that arises from glial cells (astrocytes, oligodendrocytes, ependymal cells). "CDK5 also regulates glioma tumorigenicity by phosphorylating Tripartite motif containing 59 (TRIM59), a ubiquitin ligase." (PMID 37993880, 2023). "Re-expression of shRNA-resistant TRIM59 WT or S308D mutant rescued p-STAT3, PIM1 mRNA expression, glioma sphere formation, and tumorigenesis of intracranial xenografts, but inhibited mH2A1 protein levels." (PMID 31488827, 2019). "Compared with the shRNA control, knockdown of TRIM59 significantly inhibited p-STAT3, PIM1 mRNA expression, glioma sphere formation, and tumorigenicity of intracranial xenografts, but increased mH2A1 protein levels." (PMID 31488827, 2019). "CDK5 phosphorylates TRIM59, leading to its nuclear translocation where it will initiate the ubiquitination and degradation of macroH2A1, a tumor-suppressive histone; this eventually results in increased STAT3 signaling and glioma tumorigenicity." (PMID 33665742, 2021). "TRIM59 also exerts an oncological effect on gliomas through a mechanism not dependent on its E3 ligase activity." (PMID 33665742, 2021). "Both erlotinib and Roscovitine treatments markedly inhibited TRIM59 nuclear translocation, p-STAT3, PIM1 mRNA expression, and glioma sphere formation, but increased mH2A1 protein levels, validating our observations in LN229/EGFR GBM cells." (PMID 31488827, 2019). "We showed that CDK5 regulates glioma tumorigenicity by promoting TRIM59 nuclear translocation via PIN1/importin α5 axis, leading to STAT3 signaling activation, and demonstrate that CDK5 mediates EGFR-stimulated STAT3 signaling through activation of the TRIM59/mH2A1 axis in GBM." (PMID 31488827, 2019).
liver cancer (3 papers, 2019 to 2022). An epithelial or non-epithelial malignant neoplasm that arises from the liver. "Our results indicated that the increased expression of TRIM28, TRIM37, TRIM45, and TRIM59 in liver cancer tissues likely plays a pivot role in HCC." (PMID 35142083, 2022). "Xue detected the high expression of TRIM59 protein in liver cancer tissues of patients with liver cancer, the difference was statistically significant." (PMID 31770215, 2019).
lung adenocarcinoma (3 papers, 2019 to 2026). A carcinoma that arises from the lung and is characterized by the presence of malignant glandular epithelial cells. "The results indicated that the expression of oncoprotein TRIM59 positively correlates with Cyclin CDK6 expression in Wang cell line 2 (A549 cells) and Lee Lung (lung adenocarcinoma and squamous cell lung carcinoma tissue)." (PMID 30515965, 2019).
cervical cancer (2 papers, 2019 to 2022). A primary or metastatic malignant neoplasm involving the cervix. "Several studies reported that TRIM59 is upregulated in various tumors, such as breast, gastric, colon, lung, and cervical cancer, contributing to tumor proliferation, metastasis, and angiogenesis." (PMID 31600735, 2019).
colitis (2 papers, 2024 to 2025). Inflammation of the colon. "To address this, we generated macrophage-specific TRIM59 conditional knockout mice and utilized these mice to establish colitis-associated cancer and MC38 transplanted CRC models for further investigation." (PMID 38992114, 2024). "To investigate the role of TRIM59 in colitis and cancer, we generated TRIM59f/f Lyz2-cre mice with a conditional knockout of TRIM59 specifically in macrophages." (PMID 38992114, 2024).
esophageal cancer (2 papers, 2023 to 2026). A primary or metastatic malignant neoplasm involving the esophagus.
hepatocellular carcinoma (2 papers, 2019 to 2020). A malignant tumor that arises from hepatocytes. "TRIM59 promotes tumor growth in hepatocellular carcinoma and regulates the cell cycle by degradation of protein phosphatase 1B." (PMID 32867817, 2020).
Infertility (2 papers, 2018 to 2025). "More broadly, our findings are relevant to understand the impact of Trim59 on human infertility and embryonic lethality." (PMID 29467473, 2018). "In our study, we sought to investigate the possible involvement of the ELOVL2, TRIM59, C1orf132, FHL2, and KLF14 genes in reproductive aging, infertility, and outcomes of ART." (PMID 40558830, 2025).
Lewis lung carcinoma (2 papers, 2020 to 2025). "Lewis lung carcinoma (LLC) cells release exosomes with overexpressed tripartite motif-containing 59 (TRIM59)." (PMID 41294803, 2025). "Lewis lung carcinoma (LLC) cells were injected via subcutaneously or tail vein into C57BL/6 wild-type (WT) and transgenic mice to assess the role of TRIM59 in vivo." (PMID 32867817, 2020).
lymph node metastasis (2 papers, 2019 to 2024). "TRIM59 is also upregulated and associated with tumor size and lymph node metastasis, indicating poor prognosis in CRC." (PMID 38678238, 2024). "In this study, high TRIM59 expression was significantly correlated with lymph node metastasis, distant metastasis, and tumour stage." (PMID 30515965, 2019). "Univariate analysis of 92 cases of LC demonstrated that TRIM59 expression levels was significantly correlated with lymph node metastasis, distant metastasis, and TNM stage." (PMID 30515965, 2019).
Rb (2 papers, 2021 to 2022). "In Rb tumors, MAPK pathway has been found to be up-regulated by tripartite motif-containing protein 59 (TRIM59)." (PMID 35359459, 2022). "TRIM59 is a potent oncogene whose overexpression is observed in a wide variety of human Rb cell lines including Y79, WERI-Rb-1and HXO-Rb44 indicative of its predominant role in Rb tumors." (PMID 35359459, 2022).